EHMT1 (euchromatic histone lysine methyltransferase 1)
Diseases named in the same sentence as EHMT1 in open-access papers (continued):
Sharing a sentence is not in itself a finding about the gene and the disease.
Kleefstra syndrome (continued). "Heterozygous mutations or deletions of the human Euchromatin Histone Methyltransferase 1 (EHMT1) gene are the main causes of Kleefstra syndrome, a neurodevelopmental disorder that is characterized by impaired memory, autistic features and mostly severe intellectual disability." (PMID 28071689, 2017). "Heterozygous loss of EHMT1/GLP causes Kleefstra syndrome (OMIM number 610253)." (PMID 25880195, 2015). "Moreover, EHMT1 loss of function results in Kleefstra syndrome, characterized by severe intellectual disability, developmental delays and psychiatric disorders." (PMID 25400900, 2014). "A recent study suggested that the developmental impairments observed in EHMT1-deficient networks may result in a temporal misalignment between activity-dependent developmental processes, thereby contributing to the pathophysiology of Kleefstra syndrome." (PMID 40469903, 2025). "The role of EHMT1 in Kleefstra syndrome highlights the significance of proper H3K9 methylation in regulating gene expression during neurodevelopment." (PMID 40469903, 2025). "These potentially targetable disorders include NDDs like Coffin-Siris syndrome (ARID1B; OMIM: 105830), Kleefstra syndrome (EHMT1; OMIM:610253), and Koolen-De Vries syndrome (KANSL1; OMIM: 610443)." (PMID 40400017, 2025). "One of these cases, an INV9 mappable only in de novo assembled lrGS data using T2T-CHM13 disrupts EHMT1 consistent with a Mendelian diagnosis (Kleefstra syndrome 1; MIM#610253)." (PMID 39486878, 2024). "Kleefstra syndrome (KS), often diagnosed in early childhood, is a rare genetic disorder due to haploinsufficiency of EHMT1 and is characterized by neuromuscular and intellectual developmental abnormalities." (PMID 38195854, 2023). "Mutations in several methyltransferase enzymes have neuronal phenotypes such as Weaver syndrome for EZH2, Kabuki syndrome for MLL2 and Kleefstra syndrome for the EHMT1/GLP1 gene underscoring their importance in neuronal development." (PMID 35295905, 2022). "To address this question, we have investigated the mechanism by which reduced EHMT1 activity leads to an altered neurodevelopmental programme in both isogenic cell models of Kleefstra syndrome and patient-derived iPSC." (PMID 36216811, 2022). "One of the few direct target genes, dysregulated in both mutants, was the Drosophila ortholog of Arc (Arc1), which also emerged as a relevant EHMT1 target in recent mouse studies into Kleefstra syndrome." (PMID 31088981, 2019). "Kleefstra syndrome (KS; OMIM #610253) is caused by haploinsufficiency of the euchromatin histone methyltransferase 1 (EHMT1) gene located at chromosome 9q34.3." (PMID 29416845, 2018). "These measures were compared with our previously reported data from Kleefstra syndrome patients with confirmed (germline) EHMT1 defects." (PMID 29416845, 2018). "In Drosophila, we demonstrate molecular convergence between trr, the KMT2C/D ortholog, and G9a, the ortholog of EHMT1, which is involved in Kleefstra syndrome." (PMID 29069077, 2017). "In the pre-exome sequencing era, around 25% of these cases were positive for EHMT1 haploinsufficiency characterizing Kleefstra syndrome." (PMID 29069077, 2017). "Previously, Ehmt1+/− heterozygous knockout mice were found to exhibit cranial abnormalities and decreased sociability, phenotypes similar to those observed in Kleefstra syndrome patients." (PMID 28071689, 2017). "NOTCH1 functions in the development of the semilunar valves and cardiac outflow tract, and deletion of EHMT1 manifests distinct features of 9q subtelomeric deletion syndrome or Kleefstra syndrome." (PMID 28211529, 2017). "Mutations in EHMT1, a gene encoding H3K9 methyltransferase, have been associated with Kleefstra syndrome (KS; OMIM 610253) which is characterized by intellectual disability, childhood hypotonia, and distinctive facial features." (PMID 28665350, 2017).
Kleefstra syndrome (continued). "Kleefstra Syndrome (KLEFS, OMIM #610253) is a rare genetic neurodevelopmental disorder caused by point mutations in EHMT1 (euchromatic histone-lysine N-methyltransferase 1) or, more frequently, by microdeletions of chromosomal region 9q34.3 (> 85% of cases), with loss of the entire gene." (PMID 40890826, 2025). "Knockout of EHMT1 in mice results in embryonic lethality, haploinsufficiency manifests as a neurodevelopmental disease called Kleefstra Syndrome, Copy Number Variations were reported in Schizophrenia, and elevated expression was found in several cancers and Alzheimer’s Disease." (PMID 39509467, 2024). "Variants in EHMT1, like those in KMT2C, have been found causative in Kleefstra syndrome." (PMID 37504561, 2023). "Of the patients with Kleefstra syndrome attributed to mutations in EHMT1, ~40–45% have cardiac defects; even in the absence of structural heart defects, cardiac arrhythmia has been observed in these patients." (PMID 37504561, 2023). "In vitro and animal model studies for EHMT1 and its variants have often focused on the neurodevelopmental aspects of Kleefstra syndrome; thus, many questions remain about the pathomechanism by which EHMT1 might contribute to congenital heart disease." (PMID 37504561, 2023). "Kleefstra syndrome (KLEFS, OMIM #610253, #617768) is a rare condition characterized by heterozygous genomic deletions at chromosome 9q34.3 removing the EHMT1 gene or EHMT1 point mutations (KLEFS1), or pathogenic variants in KMT2C on chromosome 7q36.1 (KLEFS2), mostly de novo." (PMID 33959609, 2021). "Interestingly, patients with Kleefstra syndrome can have a 9q34 chromosomal deletion containing the EHMT1 gene and display childhood obesity, thus suggesting a plausible role for EHMT1 in obesity development." (PMID 33193730, 2020). "In a cohort of patients with Kleefstra-syndrome-like appearance but no EHMT1 mutations, next-generation sequencing approaches revealed single de novo mutations in five novel candidate genes (MBD5, SMARCB1, KMT2C, NR1I3 and MTMR9) in four patients." (PMID 31088981, 2019). "Patients with Kleefstra syndrome who test negative for EHMT1 gene mutations may also have mutations in other epigenetic regulatory factors, such as lysine-specific methyltransferase like KMT2C." (PMID 39976094, 2025). "In addition to EHMT1 mutations, de novo variants were reported in four additional genes (MBD5, SMARCB1, NR1I3, and KMT2C), in single individuals with clinical characteristics overlapping Kleefstra syndrome." (PMID 29069077, 2017). "Furthermore, EHMT1 has been shown to play a role in DNMT1-mediated DNA methylation via UHRF1/LIG1 interaction, which implies that astrocytes might contribute to the neuronal phenotypes in SETDB1-associated disorders or Kleefstra syndrome." (PMID 33263776, 2021). "Actually, EHMT1 haploinsufficiency is involved in intellectual disability (ID) and ASD as part of the Kleefstra syndrome." (PMID 30747104, 2019). "Accordingly, during neural cell differentiation a consequence of the EHMT1 truncated protein may be disruption of the REST/EHMT1 complex, which leads to the perturbations in gene expression observed in Kleefstra Syndrome." (PMID 35139903, 2022).
Intellectual disability (20 papers, 2011 to 2026). "Kleefstra syndrome 1 (KS1), a rare genetic disorder, is caused by haploinsufficiency of the EHMT1 gene and is characterized by intellectual disability (ID), childhood hypotonia, and distinctive facial features." (PMID 37817104, 2023). "This disease is characterized by severe intellectual disability, developmental delay and psychiatric disorders, and is the result of a 9q34 subtelomeric deletion and loss-of-function mutations in EHMT1." (PMID 25400900, 2014). "It is however interesting to note that although most Kleefstra patients show severe intellectual disability, recent next generation sequencing studies in autism cases has identified a patient with loss of function mutations in EHMT1 with normal intellectual performance." (PMID 28071689, 2017). "The Ehmt1+/− mouse model, which shows clear autistic features might therefore represent a face valid model for the cases of KS that are associated with autism compared to intellectual disability." (PMID 28071689, 2017). "However, some EHMT1 variants have been described in individuals presenting with autism spectrum disorder or mild intellectual disability, suggesting that the phenotypic spectrum resulting from EHMT1 alterations may be quite broad." (PMID 28057753, 2017). "Epigenetic modification of chromatin in neurons has a role in cognitive impairment and intellectual disability and EHMT1 is long established in H3K9me1 and me2, for heterochromatin formation and gene repression." (PMID 35139903, 2022). "Haploinsufficiency of EHMT1, which encodes histone H3 lysine 9 (H3K9) methyltransferase G9a-like protein (GLP), causes Kleefstra syndrome (KS), a complex disorder of developmental delay and intellectual disability." (PMID 34258564, 2021). "Therefore, a thorough characterization of the learning and memory ability of Ehmt1+/− mice in low-aversive and low-stress tests, using positive reinforcers, would improve our insight into the cognitive phenotype of this mouse model of intellectual disability." (PMID 28071689, 2017).
Obesity (13 papers, 2014 to 2025). Accumulation of substantial excess body fat. "The brown adipose-specific loss of EHMT1 results in a significant reduction in tissue-mediated adaptive thermogenesis, obesity, and systemic IR." (PMID 38166771, 2024). "EHMT1 has various functions and is associated with tumour development, obesity, embryo growth, and cardiac hypertrophy." (PMID 38166771, 2024). "Notably, patients with EHMT1 mutations develop obesity, possibly due to impaired adaptive thermogenesis." (PMID 39351529, 2024). "This reinforces the notion that haploinsufficiency of EHMT1 is causative for obesity." (PMID 25411582, 2014). "Interestingly, mutations in the human EHMT1 gene are often associated with obesity." (PMID 25812118, 2015). "Adipose-specific knockout of Ehmt1 leads to obesity and systemic insulin resistance." (PMID 39351529, 2024). "EHMT1 increases the production of UCP1, and the deletion of this EHMT1 causes insulin resistance and obesity in mice, while a haploinsuffiency is related to obesity and insulin resistance in humans." (PMID 31614705, 2019). "EHMT1 increases the production of UCP1, and the deletion of this gene causes insulin resistance and obesity in mice, while haploinsufficiency is related to obesity and insulin resistance in humans." (PMID 27528872, 2016). "Adipose-specific ablation of Ehmt1 leads to a significant reduction in BAT-mediated adaptive thermogenesis and the development of severe obesity and systemic insulin resistance." (PMID 39351529, 2024).
autism (7 papers, 2014 to 2025). Persistent deficits in social interaction and communication and interaction as well as a markedly restricted repertoire of activity and interest as well as repetitive patterns of behavior. "In lineage 1, the autism risk gene EHMT1 was highly expressed at the earliest point, followed by the sequential peak of CELF4." (PMID 39363111, 2024). "De novo variants in EHMT1 have been reported in individuals with autism, but developmental regression has not been reported." (PMID 32722525, 2020).
Anxiety (6 papers, 2014 to 2023). Intense feelings of nervousness, tension, or panic often arise in response to interpersonal stresses. "The mouse model of this disease (Ehmt1±) expresses anxiety, autistic-like traits, and aberrant social interactions with non-cagemates." (PMID 36877418, 2023). "On the one hand, a group of lines including Cdkl5−/y, Il1rapl1−/y, Ptchd1−/y, Atp6ap2Camk2a/y, Mbd5+/−, and Ehmt1+/− displayed alterations mainly in activity, repetitive behaviour, novelty exploration and anxiety (Axis 1)." (PMID 36551904, 2022). "For example, euchromatin histone methyltransferase 1 (EHMT1) mutant mice show some delay reaching developmental milestones, as well as reduced activity and exploration, increased anxiety when exposed to novel environments in the open field, or object exploration." (PMID 25531525, 2014). "This phenotype is partially replicated in excitatory-neuron specific Ehmt1 knockout mice (CaMKIIa-Cre), which also present with hypoactivity and learning deficits, but do not show an anxiety-like phenotype." (PMID 32975655, 2020).
Insulin resistance (6 papers, 2014 to 2024). Increased resistance towards insulin, that is, diminished effectiveness of insulin in reducing blood glucose levels. "G9a (aP2-Cre; Ehmt2flox/flox) and Ehmt1 (Adipoq-Cre; Ehmt1flox/flox) knockout mice develop increased adiposity, while adipose tissue-specific Ehmt1 knockout mice also present with reduced BAT thermogenesis and insulin resistance." (PMID 33193730, 2020).
autism spectrum disorder (5 papers, 2016 to 2018). A spectrum of developmental disorders that includes autism, and Asperger syndrome. "EHMT1 mosaicism in apparently unaffected parents was recently found to be associated with autism spectrum disorder and neurocognitive dysfunction." (PMID 29794985, 2018). "In addition, there have been reports of individuals with variants in EHMT1 that present with autism spectrum disorder (ASD) or schizophrenia, suggesting that the phenotypic spectrum may be much broader than is currently appreciated." (PMID 28057753, 2017).
lung carcinoma (5 papers, 2021 to 2024). "Taken together, these results indicate that EHMT1 is highly associated with the regulation of lung cancer proliferation." (PMID 34214254, 2021). "Thus, we suggest that dysregulation of EHMT1 is clearly associated with lung cancer proliferation via regulation of CDKN1A." (PMID 34214254, 2021). "Therefore, EHMT1 could become a diagnostic and therapeutic marker for lung cancers, and our findings may contribute to the development of novel approaches for the treatment of cancers that overexpress EHMT1." (PMID 34214254, 2021). "Thus, we suggest that EHMT1 overexpression is closely associated with lung cancer proliferation." (PMID 34214254, 2021). "We clearly observed the nuclear staining pattern in lung cancer tissue, and EHMT1 was significantly overexpressed in lung cancer tissues compared with normal lung and placental tissues." (PMID 34214254, 2021). "Immunohistochemical analysis indicated that the expression levels of EHMT1 are significantly elevated in human lung carcinomas compared with non‐neoplastic lung tissues." (PMID 34214254, 2021). "The A549 and H1299 cell lines were treated with siEHMT1, and the growth of these lung cancer cell lines was suppressed by EHMT1 knockdown compared with siCont transfection." (PMID 34214254, 2021). "In our study, we detected the overexpression of the histone lysine methyltransferase EHMT1 in lung cancer." (PMID 34214254, 2021). "Taken together, these results indicate that EHMT1 is significantly overexpressed in lung cancer at both transcript and protein levels." (PMID 34214254, 2021). "The results of the current study indicate that CDKN1A expression is epigenetically controlled by EHMT1 expression in lung cancer." (PMID 34214254, 2021). "Taken together, these results demonstrated that EHMT1 knockdown increased CDKN1A expression in lung cancer cell lines and that upregulation of CDKN1A expression induced cell cycle arrest and apoptosis." (PMID 34214254, 2021). "Here, we confirmed that EHMT1 expression is upregulated in lung cancers via immunohistochemistry and that EHMT1 expression is upregulated in several types of cancers via analysis of GENT and RNA‐seq lung cancer data from the TCGA portal." (PMID 34214254, 2021). "Next, to verify the function of EHMT1 in lung cancer, we performed RNA‐seq analysis of siEHMT1‐ versus siCont‐transfected H1299 cells." (PMID 34214254, 2021). "Knockdown of EHMT1 in lung cancer cell lines upregulated CDKN1A expression and induced both apoptosis and cell cycle arrest." (PMID 34214254, 2021). "Lee J and colleagues explored the effect of EHMT1 on lung cancer." (PMID 36092868, 2022). "We used a 3D spheroid system to confirm the results from the 2D culture system study, implying that we could expect a similar anti‐EHMT1 effect in a xenograft model derived from lung cancer cell lines." (PMID 34214254, 2021). "Therefore, the development of EHMT1‐specific inhibitors is needed for lung cancer and other cancers." (PMID 34214254, 2021). "Moreover, we confirmed the effects of EHMT1 on lung cancer proliferation via GO analyses of RNA‐seq data and found that it is particularly involved in the cell cycle and cell apoptosis." (PMID 34214254, 2021). "In this study, we found that EHMT1 is overexpressed in lung cancer and that EHMT1 modulates CDKN1A gene expression through the regulation of chromatin functions, subsequently promoting the proliferation of cancer cells by allowing them to evade apoptosis and cell cycle arrest." (PMID 34214254, 2021). "Additionally, EHMT1 was significantly overexpressed in lung cancer samples (n = 533) compared to normal lung samples (n = 59) according to RNA sequencing (RNA‐seq) data derived from The Cancer Genome Atlas (TCGA) portal." (PMID 34214254, 2021). "Moreover, cell cycle analysis revealed that G1 arrest by EHMT1 knockdown was attenuated by CDKN1A knockdown in lung cancer cell lines." (PMID 34214254, 2021).